RN7SL776P (RNA, 7SL, cytoplasmic 776, pseudogene)
Gene: Miscellaneous RNA gene on chromosome 4 (167,400,495 to 167,400,762, reverse strand). Ensembl gene ENSG00000240772.
Homologues: Orthologues: chimpanzee Metazoa_SRP (99% identical), macaque Metazoa_SRP (92% identical). Paralogues in human: RN7SL2 (78% identical), RN7SL3 (77% identical), RN7SL1 (77% identical), RN7SL589P (77% identical), RN7SL296P (76% identical), RN7SL408P (75% identical), RN7SL448P (75% identical), RN7SL230P (75% identical), RN7SL398P (75% identical), RN7SL615P (75% identical), RN7SL660P (75% identical), RN7SL126P (75% identical), and 704 more.